EGFR (epidermal growth factor receptor)
Diseases named in the same sentence as EGFR in open-access papers (continued):
Sharing a sentence is not in itself a finding about the gene and the disease.
cancer (continued). "In our previous studies, we have characterized the conformational landscapes of ABL, EGFR, RET and MET kinases as well as various cancer mutants using MD simulations of the Apo kinase and complexes with ATP and small molecule inhibitors." (PMID 21998754, 2011). "EGFR-MEK-ERK signaling pathway has an established role in promoting malignant growth and disease progression in human cancers." (PMID 21445343, 2011). "The receptor tyrosine kinases (RTKs) and drug targets EGFR, ERBB2 and MET were each amplified (log2 > 0.6) and overexpressed at the RNA level in one cancer sample." (PMID 21781349, 2011). "Via direct transcriptional activation, ΔNp63α leads to the up-regulation of epidermal growth factor receptor (EGFR) and 14-3-3σ, sensitizing cancer cells to EGF and enhancing their oncogenic potential." (PMID 22053213, 2011). "The EGFR-Ras-Raf-MEK-ERK signaling pathway has been the subject of intense research and pharmaceutical scrutiny to identify novel target-based approaches for cancer treatment." (PMID 21939503, 2011). "We exploit this expression through the development of EGFR-targeted, polymer blend nanocarriers for the treatment of MDR cancer using paclitaxel (a common chemotherapeutic agent) and lonidamine (an experimental drug; mitochondrial hexokinase 2 inhibitor)." (PMID 21931642, 2011). "A study demonstrated that the nuclear EGFR can cooperate with STAT5A to target the promoter region of AURORA-A and enhance its expression in cancer cells." (PMID 21865609, 2011). "Because many solid tumors, including HNSCC have hyper activated epidermal growth factor receptor (EGFR), there has been great interest in the use of EGFR inhibitors to control cancer growth." (PMID 22242139, 2011). "EGFR interacts with and stabilizes the sodium/glucose cotransporter (SGLT1) in order to promote glucose uptake into cancer cells." (PMID 22035226, 2011). "EGFR-specific CTL from cancer patients were expanded ex vivo and produced IFN-γ upon recognition of EGFR+ target cells." (PMID 21970318, 2011). "The EGFR and VEGF receptor (VEGFR) share common downstream pathways and exert their effects directly and indirectly on cancer cells." (PMID 21750552, 2011). "Recent studies indicated that curcumin was able to down-regulate EGFR and HER2/neu protein kinase activity which inhibits the cancer cells growth." (PMID 21858220, 2011). "In cancer cells, the CPP blocked P-YB-1S102 and down-regulated both HER-2 and EGFR transcript level and protein expression." (PMID 20844753, 2010). "The rationale for developing this dual EGFR/HER2 TKI was to sustain synergistic inhibition of cancer cells by simultaneously targeting receptors in both cell lines, resulting in more potent inhibition in cell growth than could be achieved by targeting either EGFR or HER2 alone." (PMID 21050422, 2010). "The cycloxygenase-2 (COX2), the epidermal growth factor receptor (EGFR) ligand HB-EGF, and the α2, 6-sialyltransferase (ST6GALNAC5) were identified as mediators in cancer cell extravasation and infiltration through the BBB." (PMID 21253507, 2010). "Nielsen at al. determined that 13 of 21 basal-type cancers from microarray study were CK5/6-positive by immunohistochemistry, 12 of them were EGFR-positive, and 6 of them were c-KIT-positive." (PMID 20426817, 2010). "First, EGFR activation drives MAPK signaling, which leads to its upregulation in a number of aggressive cancers." (PMID 20628489, 2010). "Considering recent evidence suggesting that PTEN mutation results in resistance to EGFR-targeted therapies, the inhibition of TOPK in KRAS and BRAF wild-type patients could represent an approach to improve clinical outcome in patients with either PTEN wild-type or mutated cancers." (PMID 19935791, 2010). "Basal-like cancer cells commonly express some of the basal cell markers such as cytokeratin 5 (CK5) and 17 (CK17), as well as caveolin-1, EGFR, B-crystallin, P-cadherin, and c-KIT." (PMID 20979652, 2010).
cancer (continued). "RTKs like epidermal growth factor receptor (EGFR) and epidermal growth factor receptor 2 (Her2/ERBB2) are overexpressed or activated in a variety of human cancers." (PMID 21049007, 2010). "An exciting, novel concept in cancer chemoprevention may be the use of combination therapy, which may allow dose reduction (and hence decreased systemic bioavailability) of NSAIDs or coxibs when combined with other anti-cancer agents, e.g., epidermal growth factor receptor inhibitors." (PMID 27713364, 2010). "In other study, it has been revealed a surprising link between glucose uptake performed by SGLT1, survival of cancer cells, and EGFR (epidermal growth factor receptor), whose malfunction is involved in many carcinogenetic processes." (PMID 20706540, 2010). "Several subtypes of common cancers have been identified based on alterations of individual cancer genes, such as HER2, EGFR, and others." (PMID 20569491, 2010). "Amplification of the membrane receptor genes EGFR and FGFR1 has been reported in various cancers including ESCC, and this phenomenon has been suggested to be a poor prognostic factor in solid tumors." (PMID 20163722, 2010). "In recent years, the epidermal growth factor receptor (EGFR – particularly HER-1 and HER-2) has been the most extensively investigated TKs and now forms a significant component of the ongoing research into molecular targeted cancer therapy." (PMID 21063399, 2010). "Retargeting has been achieved through the conjugation of antibodies directed against CD59, CD71, transferrin, EGFR or cholera toxin B to fiber-modified BAP vectors, resulting in enhanced infection in CAR-negative carcinoma cell lines." (PMID 21994621, 2010). "EGFR and the EGF-family of peptide growth factors play a central role in the pathogenesis and progression of different carcinoma types." (PMID 20565817, 2010). "Twenty seven out of 49 (55.1%) carcinomas displayed positive immunostaining for both TGF-α and EGFR." (PMID 21087480, 2010). "We have previously determined that lapatinib inhibits the heterodimer of EGFR and HER2 in cancer cells." (PMID 19529774, 2009). "A comparative analysis has been conducted based on computational modeling of the wild type (WT) ABL and EGFR kinase domains as well as a panel of clinically important cancer mutants ABL-T315I, ABL-L387M, EGFR-T790M, and EGFR-L858R." (PMID 19714203, 2009). "Structural determinations of the EGFR and ABL cancer mutants have suggested that molecular mechanisms of kinase activation by cancer mutations and activity signatures of cancer drugs may be associated with the dynamics of functional transitions between inactive and active kinase forms." (PMID 19834613, 2009). "The epidermal growth factor receptor (EGFR) is a receptor tyrosine kinase involved in normal cellular growth and differentiation as well as in the pathogenesis of cancer." (PMID 19531065, 2009). "Using a battery of computational approaches, we have systematically investigated the effects of clinically important cancer mutants on dynamics of the ABL and EGFR kinase domains and regulatory multi-protein complexes." (PMID 19714203, 2009). "Lapatinib (GW572016, Tykerb) is a dual synthetic reversible inhibitor of EGFR and HER2 tyrosine kinases, and has been demonstrated to inhibit significantly the proliferation of cancer cells evidencing EGFR and/or HER2 overexpression both in vitro and in vivo." (PMID 19529774, 2009). "A major EGFR signalling route, the mitogen-activated protein kinases (MAPK) pathway is often deregulated in cancer cells." (PMID 19654571, 2009). "Using bispecific antibodies for the simultaneous blocking of EGFR and IGF-1R significantly intensified the response of cancer cells when compared with monospecific antibodies." (PMID 22649585, 2009). "Consistent with the results observed with TS downregulation, co-transfection with EGFR and HER2 siRNA induced a profound G1-arrest of cancer cells." (PMID 19529774, 2009).
cancer (continued). "Epidermal growth factor receptor (EGFR) controls a wide range of cellular processes, and altered EGFR signaling contributes to human cancer." (PMID 19948031, 2009). "Generation of small molecule inhibitors that specifically block the EGFR and GEP100 binding, or interact with the GEP100 Sec7 domain will be useful for cancer therapeutics." (PMID 19416474, 2009). "Lapatinib, an orally active, small molecule, reversible inhibitor of EGFR and HER2, is being evaluated for treatment of cancers with EGFR expression and HER2 overexpression, including cancers that are refractory to standard therapy." (PMID 19844234, 2009). "Lapatinib blocks ligand-activated signaling from multiple receptor combinations, including homo-and heterodimers of EGFR and HER2; preclinically, it inhibits the proliferation of trastuaumab-resistant cancer cells." (PMID 19529774, 2009). "The central role of HER2 and EGFR in growth and differentiation of both normal and malignant cancer cells and their availability to extracellular manipulation make both HER2 and EGFR attractive targets for pharmacological intervention." (PMID 18334972, 2008). "There is strong evidence that EGFR and VEGF play a role in carcinogenesis and progression in many human cancers." (PMID 19014499, 2008). "Next to mAbs, another class of drugs is successfully employed to target EGFR for cancer therapy: small molecule tyrosine kinase inhibitors (TKI), targeting the ATP-binding pocket of the EGFR kinase domain." (PMID 18702090, 2008). "Biochemical analysis demonstrated that enzastaurin inhibits the expression of pAkt in all of the cancer cell lines examined and suppresses the expression and secretion of VEGF, especially in those cell lines resistant to EGFR inhibitors." (PMID 18665191, 2008). "EGCG inhibits the activation of EGFR (erbB1), HER2 (neu/erbB2) and also HER3 (neu/erbB3), which belong to subclass I of the RTK superfamily, in various types of human cancer cells." (PMID 19325845, 2008). "In the present study, we have investigated the effect on growth and protein expression of enzastaurin, used alone and in combination with the EGFR TKI gefitinib, in human cancer cells sensitive or resistant to gefitinib, in vitro and in nude mice." (PMID 18665191, 2008). "PI3K and Akt kinases operate downstream of EGFR and HER2 in cancer cells, transmitting signals that regulate cell survival and cell migration." (PMID 18822183, 2008). "Although EGFR and HER2 have been viewed as prototype oncogenes that can drive tumorigenesis through their constitutive activation in cancers, evidence is mounting that their trans-signalling functions are essential aspects of their oncogenic functions." (PMID 17667926, 2007). "pan-DVL knockdown lowered EGFR activity, as shown by a decrease in pY845 levels, and strongly reduced ERK1/2 activity in each of these cancer cell lines." (PMID 17897439, 2007). "Among these components, epidermal growth factor receptor (EGFR), a membrane protein, has been well studied for its function in cancer biology." (PMID 19662227, 2007). "The mediation model explained and confirmed the EGFR and p-AKT pathway and its effect on cancer development in OS patients with reasonable satisfaction." (PMID 19662227, 2007). "There are currently four known ErbB receptors with ErbB1 (also known as EGFR) and ErbB2 (also known as Neu or HER2) being the most likely to be overexpressed in cancers, and, therefore, the most studied." (PMID 16519802, 2006). "Gefitinib is an epidermal growth factor receptor (EGFR) tyrosine kinase (TK) inhibitor that blocks signal pathways involved in proliferation and survival of cancer cells." (PMID 16670714, 2006). "The epidermal growth factor receptor (EGFR), which induces malignant tumour via three major mechanisms such as overexpression, amplification and mutational activation, appears to be molecular target for therapeutic development." (PMID 16552419, 2006).
cancer (continued). "Although EGFR was shown to have no independent prognostic significance in advanced cancer, the EGFR and HER2/neu were frequently overexpressed in malignant tumours." (PMID 15655552, 2005). "EGFR signaling involved in cell growth, angiogenesis, DNA repair, and autocrine growth regulation in NSCLC as well as in a wide spectrum of human cancer cells." (PMID 15987532, 2005). "Heregulin, a combinatorial ligand for EGFR 3 and 4, has earlier been found to upregulate ATF4 mRNA as well as ATF4 protein in human cancer cells." (PMID 15846300, 2005). "ZD1839 (‘Iressa’), an orally active, selective epidermal growth factor receptor (EGFR) tyrosine kinase inhibitor, is currently being investigated in clinical trials as a treatment for cancer." (PMID 12888834, 2003). "The anti-cancer effects of saracatinib were mediated through inhibition of p38 mitogen-activated protein kinase (MAPK), extracellular signal-regulated protein kinase (ERK), or epidermal growth factor receptor (EGFR) signaling pathways." (PMID 42065072, 2026). "The rationale for dual-targeting of both EGFR and c-MET besides heterogeneous expression is that an interplay between EGFR and c-MET expression is seen in cancer cells, where therapeutic targeting of one receptor leads to compensatory mechanisms and upregulation of the other receptor." (PMID 41552759, 2026). "MP1 was modified by addition of sequences allowing binding to the cancer biomarker EGFR, with or without sequences directing cleavage by the cancer biomarker MMP-2." (PMID 41920242, 2026). "Furthermore, the compounds were evaluated for their effects on cancer cell viability through in vitro MTT assays (as an exploratory endpoint) and for their binding compatibility with EGFR via in silico docking." (PMID 42188316, 2026). "Although previous studies in various in vitro cancer models have evaluated EGFR and PI3K inhibitor combination, these studies did not investigate the role of EGFR amplification in addition to PI3K mutation status as biomarkers for drug synergy." (PMID 41291067, 2026). "Moreover, research has predominantly focused on broadly expressed pan-cancer biomarkers, such as PTK7, nucleolin, and EGFR, while studies specifically addressing biomarkers unique to rare cancers remain scarce." (PMID 41560835, 2026). "Therapeutic interventions targeting epidermal growth factor receptor (EGFR) and anaplastic lymphoma kinase (ALK) have significantly improved the treatment of metastatic lung cancer by interfering with signaling pathways essential to cancer progression." (PMID 41596524, 2026). "By integrating network pharmacology prediction and molecular docking technology, this study is the first to reveal the core mechanism by which IPTF exerts anti-cancer effects through the synergistic regulation of the PI3K/AKT and EGFR-MAPK dual signaling pathways." (PMID 41008250, 2025). "The EGFR-driven Fc-effector functions were also observed in other cancer cell lines (data not shown)." (PMID 40452841, 2025). "Moreover, EGFR and IGF-IR are key players in cancer progression, triggering signaling cascades that influence multiple cellular behaviors such as cell survival and proliferation, metabolic reprogramming, resistance to apoptosis, EMT, invasion and metastasis." (PMID 40943584, 2025). "All these data demonstrated that our developed degradation system could degrade EGFR mutants and inhibit HDAC activity in both gefitinib‐resistant and osimertinib‐resistant lung tumor tissues and exhibited potent in vivo anti‐cancer effect with good safety." (PMID 40842076, 2025). "Results were grouped based on distinct cancer types (breast, lung, prostate) and specific nAChR subtypes (e.g., α7, α9, α5), aligning them with their relevant key signaling pathways (e.g., EGFR/ERK1/2, PI3K/AKT, MAPK), and summarizing their contributions to cancer progression." (PMID 41218914, 2025).
cancer (continued). "Remarkably, the mere activation of Wnt/ERK/CDK4/6 in E/M cells suffices to cement a programme integrating cancer stem cell maintenance (via FOXC2/p63) and self-renewal (via S-phase and FOXM1 activation) with inhibition of differentiation (via EGFR inactivation)." (PMID 40764669, 2025). "Thus, the concurrent inhibition of both EGFR and VEGFR-2 has arisen as an effective cancer therapeutic strategy, producing a synergistic impact (Liu Z.-L." (PMID 40395767, 2025). "The paper further emphasizes that intestinal bacteria and their metabolites can directly or indirectly regulate several signaling pathways relevant to cancer therapy, including VEGFR, EGFR, and HER2, thereby influencing cancer growth, metastasis, and therapeutic responses." (PMID 39948481, 2025). "Examining the co-expression patterns of EGFR and AXL in various cancers could provide valuable insights into potential biomarkers." (PMID 39924521, 2025). "The ErbB receptor family includes specific transmembrane tyrosine kinase proteins: epidermal growth factor receptor, also known as ErbB1; ErbB2, also known as HER2; ErbB-3; and ErbB-4, all of which are overexpressed to varying degrees in human cancer including HNSCC." (PMID 40675157, 2025). "However, the widespread expression of EGFR in various tissues and organs is a key concern, especially for long-term consequences in CAR-T therapy for cancer." (PMID 40722671, 2025). "Additionally, we performed moleculardocking and molecular dynamics (MD) studies of EGFR, RIPK1 and RIPK3,key proteins in necroptosis, to investigate lamivudine’s abilityto induce cancer cell death." (PMID 40384113, 2025). "Our data are consistent with the notion that dual targeting of EGFR and TGFBR may be most effective in blocking cancer cell invasion and metastasis." (PMID 40859866, 2025). "Moreover, copper depletion in cancer cells inhibits the phosphorylation of STAT3, epidermal growth factor receptor (EGFR), AKT and GSK3β." (PMID 39744687, 2025). "There are ongoing efforts to study the combination of EGFR inhibitors together with ICI (NCT03944941), and meanwhile, previous studies have shown that the combination of cytotoxic chemotherapy and ICI is effective for other cancer types." (PMID 40692904, 2025). "Additionally, the top hub genes identified in the PPI network of FZD4 miRNA targets, including MYC, EGFR, MDM2, and CDK1, were also involved in many aspects of cancer progression." (PMID 40667070, 2025). "Given its influence over various oncogenic mechanisms including the PI3K/AKT, EGFR, Src, and WNT pathways, AR dysregulation plays crucial roles in promoting the proliferation and progression of certain cancers such as prostate, breast, liver, and ovarian malignancies." (PMID 39744510, 2025). "Given the clinical relevance of EGFR signaling in cancer, understanding TARG1’s function could have significant therapeutic implications, particularly in tumors reliant on EGFR-driven proliferation and migration." (PMID 40603466, 2025). "KEGG pathways related to cancer and focal adhesion suggest that the binding of OTA to EGFR may enhance the oncogenic potential of prostate cells." (PMID 40864064, 2025). "Through systematic optimization of the immobilization of antibody molecules and the anti‐fouling strategy of the sensing interface, the sensing platform demonstrates the capability to detect trace amounts of cancer markers, such as MIF, EGFR, and GPC1, within intricate biological media." (PMID 40598854, 2025). "The enhancement of PI3K-Akt and EGFR signalling pathways, recognised as key contributors to CCA progression, further emphasises the potential of medicarpin as a multi-target treatment candidate for this cancer." (PMID 41465766, 2025). "Additionally, terms related to signaling axes that are commonly hijacked by cancer cells, such as terms related to ALK, TROP2, and TOB1, which is a growth-suppressive factor, and EGFR and ERBB (leading genes DAB2IP and PTPRJ) were enriched in both analyses." (PMID 40564222, 2025).